ESX1 (ESX homeobox 1)
Diseases named in the same sentence as ESX1 in open-access papers (continued):
Sharing a sentence is not in itself a finding about the gene and the disease.
infection (continued). "The role of the ESX-1 system in infection and pathogenesis has been studied in depth, and the WXG100 family substrates ESAT-6 and CFP-10 are important virulence factors secreted by ESX-1." (PMID 38116759, 2023). "It was previously reported that N-terminal acetylation of EsxA was required for ESX-1 function during infection." (PMID 37772840, 2023). "While ESX-1-dependent bacterial growth may contribute to promoting the accumulation of neutrophils, their recruitment preceded ESX-1-dependent bacterial growth, and linear regression analysis indicated a lack of association between neutrophil accumulation and bacterial growth in WT infection." (PMID 37017530, 2023). "This requirement was enhanced in mice lacking Rag2, Ifng, or Nos2, consistent with the preferential role of ESX1 during the initial stage of infection before the initiation of adaptive immunity, which is prolonged in these immunodeficient strains." (PMID 35112666, 2022). "The genes we identified by TnSeq with mL2-specific differential requirements during infection represent key adaptive processes, including the ESX-1 virulence system, lipid metabolism, and DNA damage repair." (PMID 35430871, 2022). "espR regulates the ESX-1 virulence system, which was differentially required by the mL2 strain during infection." (PMID 35430871, 2022). "In Mtb, ESAT-6, or EsxA, was shown to promote virulence in a murine model of infection and the ESX1 system that secretes EsxA has been well established as necessary for phagolyosomal escape and intracellular survival in macrophages." (PMID 34871327, 2021). "The recent development of selective ESX-1 inhibitors such as BTP15 allowed us to conditionally shut down secretion of ESX-1 effector proteins 5 h after infection of GSDMD knock-out macrophages." (PMID 34718331, 2021). "In the early stage of infection, both M. tuberculosis and the phylogenetically closely related M. kansasii use a type VII secretion system, encoded by ESX-1 genes, to secrete essential virulence factors, such as ESAT-6 and CFP-10." (PMID 34504483, 2021). "Similar to findings for MYD88, expression of representative genes upon infection with wild-type Mtb or PDIM or ESX-1 mutants was entirely lost in Tlr2-/- BMDM." (PMID 34755600, 2021). "Our results demonstrating an interaction between TLR2 and PDIM or ESX-1 for infection outcome suggest that undermining this second component contributes to Mtb’s success as a pathogen." (PMID 34755600, 2021). "PDIM has been described to specifically contribute to macrophage necrosis; ESX-1 has also been shown to contribute to macrophage cell death after infection." (PMID 34755600, 2021). "Infection with Mycobacterium tuberculosis (Mtb) phthiocerol dimycocerosate (PDIM) or ESX-1 mutants elicits enhanced expression of an inflammatory transcriptional program." (PMID 34755600, 2021). "In agreement, zebrafish infections show that wild type M. marinum bacteria are decorated by ubiquitin and GFP-Lc3, indicative of a selective autophagy response, whereas ESX-1-deficient bacteria hardly elicit GFP-Lc3 recruitment." (PMID 33138004, 2020). "ESX-1 in M. marinum is crucial for parasitism of amoebae, mammalian phagocytes, and zebrafish models of infection." (PMID 31896783, 2020). "Using RNA-seq, we identify ESX-1-dependent transcriptional responses in iPSDMs after infection with Mtb." (PMID 32938685, 2020). "ESX-1 is crucial for survival within the macrophage during early infection, mediating evasion of bacterial killing and induction of growth-permissive responses." (PMID 32701962, 2020). "Infection with ESX-1-deficient bacteria is strongly attenuated in the zebrafish host, which is explained by the requirement of ESX-1 for escape of Mycobacteria into the cytosol and consequent macrophage responses and granuloma formation." (PMID 33138004, 2020).
infection (continued). "ESX-1 [early secreted antigen 6 kilodaltons (ESAT-6) system 1] is one of the five subtypes (ESX-1~5) of T7SSs in Mtb, where it delivers virulence factors into host macrophages during infection." (PMID 31758528, 2020). "Mycobacterial pathogens use the ESX-1 system to transport protein substrates that mediate essential interactions with the host during infection." (PMID 32019792, 2020). "During the first stages of infection, ESX-1-mediated protein secretion is one of the most important virulence mechanisms of pathogenic mycobacteria." (PMID 30673778, 2019). "Taken together, these data show that WhiB6 is required for the secretion-dependent regulation of ESX-1 substrates and that ESX-1 substrates are regulated independently from the structural components, both during infection and as a result of active secretion." (PMID 30673778, 2019). "Taken together, our results show that transcription of the espA locus plays an important role in ESX-1 mediated processes during the first hours of infection." (PMID 30673778, 2019). "The mycobacterial type VII secretion system ESX-1 is responsible for the secretion of a number of proteins that play important roles during host infection." (PMID 30673778, 2019). "Using transcriptome sequencing, we found that the abrogation of ESX-1 function in Mycobacterium marinum leads to a pronounced increase in gene expression levels of the espA operon during the infection of macrophages." (PMID 30673778, 2019). "We next determined the effect of ESX-1 abrogation in M. marinum on gene transcription during infection of primary macrophages." (PMID 30673778, 2019). "The pathogen Mycobacterium tuberculosis employs a range of ESX-1 substrates to manipulate the host and build a successful infection." (PMID 30102741, 2018). "These structures were significantly less abundant upon infection with M. marinum ΔRD1, an attenuated mutant that produces PDIMs but lacks the ESX-1 secretion system." (PMID 30596802, 2018). "Mouse infection experiments utilizing M. tuberculosis with a partial deletion in ESX-1 showed reduced granuloma formation, the characteristic pathological hallmark of mycobacterial disease." (PMID 30102741, 2018). "Some studies have demonstrated an attenuated phenotype in mouse models of infection following inactivation of esxA and esxB or other genes of the ESX-1 secretion system of M. tuberculosis." (PMID 29653505, 2018). "Together, these data show that different sets of ESX-1 substrates play different roles at various steps of the infection cycle of M. marinum." (PMID 30102741, 2018). "In the case of M. tuberculosis, phagosomal damage depends upon the ESX-1 secretion system and has been most definitively demonstrated after several days of infection." (PMID 30482832, 2018). "The ESX-1 secretion defect prevents several virulence factors from being functional during infection and therefore attenuates M.tb." (PMID 28436493, 2017). "Another factor essential for optimal M. marinum intracellular growth is the ESX-1 secretion system, responsible for the rupture of the phagosomes containing M. marinum and its release into D. discoideum cytosol at the end of this infection phase (21–37 hpi)." (PMID 29376033, 2017). "ESX-1 is also needed for the release of Mtb DNA and translocation of Mtb into the cytosol during infection." (PMID 28806745, 2017). "The ESX-1 secretion system is a major virulence determinant of M. tuberculosis that mediates secretion of mycobacterial products that shape host responses to infection." (PMID 29230217, 2017). "Generally Esx-1-mediated protein secretion into culture medium during bacteriological growth correlates with virulence in ex vivo and in vivo infection models." (PMID 27625110, 2016). "In ex vivo cellular infection models the Esx-1-system perforates the phagosomal membrane promoting interaction between the mycobacterial cell and the cytosol of the macrophage and modulation of the host innate immune response." (PMID 27625110, 2016).
infection (continued). "Accordingly, reducing macrophage demand (e.g., ESX-1 mutant infection) not only delays necrosis in wild-type animals but also greatly curtails necrosis even under conditions of reduced macrophage supply." (PMID 26159717, 2015). "To ask if macrophage demand alters the time to granuloma necrosis, we compared wild-type and ESX-1 mutant infection in wild-type animals." (PMID 26159717, 2015). "Upon infection of human macrophages ESX1-dependent fractalkine production mediated selective recruitment of CD11b+ monocytic cells and increased infection of neighbouring cells consistent with early local spread of infection." (PMID 24631198, 2014). "In conclusion, infection of zebrafish embryos with the ESX-1 mutant resulted in the formation of smaller clusters and a higher number of phagocytes filled with an abundant load of bacteria, as expected based on earlier publications." (PMID 24997190, 2014). "ESX1-mediated fractalkine production from infected macrophages thus results in increased influx and infection of monocytic cells and promotes bacillary dissemination." (PMID 24631198, 2014). "Data from different works provide evidence that ESX-1-induced apoptosis can contribute to virulence by spreading infection." (PMID 24364000, 2013). "Mycobacterium tuberculosis uses ESX-1 secretion system to export virulence proteins during infection." (PMID 23355891, 2013). "Having excluded a requirement for the ESX1 system in cytolytic activity we concluded that other Mtb genes must be responsible for infection-induced LMP in our system." (PMID 21483832, 2011). "Thus, Esx-1 may exert its major pathogenic role during the acute phase of infection." (PMID 20463815, 2010). "Taken together, these findings suggest that a major role for Esx-1 in vivo is to manipulate the inflammatory response during the early events of infection." (PMID 20463815, 2010). "Such analysis demonstrated a 2.6-fold increase of mature IL-1β in the tails of mice infected with wild type M. marinum compared to ΔRD1 infection, suggesting that Esx-1 promotes caspase-1 activation in vivo." (PMID 20463815, 2010). "Infection of wild type and ASC-deficient mice demonstrated that Esx-1-dependent inflammasome activation exacerbated disease without restricting bacterial growth, indicating a host-detrimental role of this inflammatory pathway in mycobacterial infection." (PMID 20463815, 2010). "Consistent with previous work, we found that infection with ESX1 mutant bacteria induced significantly less IFNβ and RANTES expression than wild type bacteria." (PMID 19578435, 2009). "After Mm infection of host cells, ESX-1 is required for bacterial escape from the phagosome, recruitment of uninfected macrophages, and subsequent cell-to-cell spread." (PMID 19436699, 2009). "Finally, we leveraged two infection models to support that ESX-1 substrate switching likely occurs during infection." (PMID 42053305, 2026). "To determine whether ESX-1 related homopolymer indels altered interactions with the host in the more complex infection environment of the intact animal, we quantified the effect of these mutations on bacterial fitness in the mouse lung." (PMID 39873486, 2025). "In addition to ESX-1, the unique lipids in the mycobacterial cell envelope have key roles in virulence and survival during infection." (PMID 40304497, 2025). "In contrast, infection with the avirulent ESX-1 deletion mutant strain resulted in diffuse and sparsely organized CD11b recruitment (median size of 8.22×107 μm3), primarily located in the lung periphery and minimally involving the airways (0.23% of the total lung space)." (PMID 40134379, 2025). "While ESX-1 plays a key role in regulating the function of myeloid cells in vitro, its impact on monocyte transcription during in vivo infection remains unclear." (PMID 39915532, 2025).
infection (continued). "While the role of ESX-1 in regulating myeloid cell transcription in vivo remains less clear, infection of mice with a BCG vaccine strain was recently found to induce similar epigenetic and transcriptional changes in alveolar and interstitial lung macrophages as M. tuberculosis." (PMID 39915532, 2025). "As such, we posit that tuning ESX-1 components up or down throughout infection may have differential fitness effects within different niches or at different timepoints." (PMID 39873486, 2025). "PhoPR and high CO2 are required for key steps of initial macrophage infection (e.g., ESX-1 secretion); therefore, inducing these pathways at the onset of infection, prior to macrophage infection, could enhance virulence." (PMID 39964175, 2025). "However, only infection with ESX-1-proficient M. marinum produced cathepsin B activity in the cytosolic compartment, suggesting that ESX-1-dependent permeabilization of the lysosomal membrane causes leakage of cathepsin B into the cytosol." (PMID 39087767, 2024). "The stochasticity of our results may suggest that ESX-1 regulatory network includes a bistable switch that operates early during infection, possibly through pairs of mutually exclusive regulators or positive autoregulation." (PMID 38445877, 2024). "Despite regulating the transcription of ESX-1 substrate genes, the deletion of whiB6 or espM does not phenocopy the loss of ESX-1 substrate genes in macrophage models of infection." (PMID 38445877, 2024). "Thus, endogenous Gal-9 is recruited to Mtb in an ESX-1-dependent manner soon after infection and maintains steady localization with a subpopulation of bacteria throughout infection." (PMID 37352334, 2023). "Thus, consistent with findings in the zebrafish infection model, our results suggest that ESX-1-dependent neutrophil accumulation cannot merely be explained as a consequence of the bacterial burden in the tissue." (PMID 37017530, 2023). "In contrast, ΔRD1 infection did not induce the formation of neutrophil-containing granulomatous structures until 28 days postinfection, and ESX-1-deficient bacteria were mainly scattered in areas of CD64+ cells." (PMID 37017530, 2023). "Importantly, these ESAT-6 mutants have near-normal levels of secretion, far higher than the minimal threshold we establish is needed for ESX-1–mediated virulence early in infection." (PMID 35271388, 2022). "The small increase in cytochrome c release in ESX-1-mutant infection suggests that additional factors may also play a role, for instance, PDIM." (PMID 36103894, 2022). "ESX-1-deficient infection also did not cause macrophage death in animals deficient in glycolysis or OXPHOS." (PMID 36103894, 2022). "The canonical Mtb virulence factors phthiocerol dimycocerosate (PDIM) and ESX-1 contribute to disruption of the macrophage phagosomal membrane upon infection; we sought to leverage this shared pathogenic effect to gain insight into compartment-specific signaling in the macrophage response to Mtb." (PMID 34755600, 2021). "Overall, our results revealed that EspC is an essential ESX-1 protein for Mtb–host interactions and EspC-induced ER stress-mediated apoptosis may be employed by Mtb to establish and spread infection." (PMID 33290182, 2021). "The ESX-1 secretion system is required for full pathogenicity and is responsible for the secretion of a set of crucial virulence factors that play a key role in the escape of mycobacteria from the phagosome to the cytosol during infection (16, –, 18)." (PMID 33653883, 2021). "However, we found that similar to Tnf transcription, TNF release upon Mtb infection was partially dependent upon MYD88 and TLR2 and very modestly increased upon infection with PDIM- or ESX-1-mutant Mtb." (PMID 34755600, 2021). "ESX-1 enhances recruitment of macrophages during infection, promoting granuloma formation." (PMID 32701962, 2020). "Simulations: Simulations of independent low-dose aerosol infections with 50 WT or esx-1 bacteria." (PMID 33228849, 2020).
infection (continued). "Since ESX-1 has been shown to be responsible for mycobacterial escape from the phagosome, which occurs within the first few hours of infection with M. marinum, the proteins produced by the espA operon may play an important role in this process." (PMID 30673778, 2019). "Zhanget al. recently reported that EspI, a protein encoded byesx-1, is indeed not essential for ESX-1 secretion during active infection but is responsible for down-regulating ESX-1 secretion during low-energy states in the bacilli." (PMID 32047597, 2019). "To study whether the individual ESX-1 proteins play a role during infection in vivo, we used the zebrafish larva-M." (PMID 30102741, 2018). "ESX-1-dependent membrane damage happens early after bacterial uptake, as host sensors present in the cytosol detect bacterial products and respond within the first hours of infection (8, 26, –, 32)." (PMID 30482832, 2018). "However, another study has also indicated that ESX-1-mediated secretion is required for the production of host type I IFNs by ESAT-6 during infection in vivo and in macrophages in vitro." (PMID 29210987, 2017). "To test the hypothesis of M. marinum blocking the autophagic flux in an ESX-1-dependent manner, we measured the flux using an improved protocol tailored to the specific infection conditions." (PMID 28414774, 2017). "Building upon the shared phenotype of loss of the macrophage type I interferon (IFN) response to infection, we found that PDIM production and export are required for coordinated secretion of ESX-1-substrates, for phagosomal permeabilization, and for downstream induction of the type I IFN response." (PMID 28505176, 2017). "For unknown reasons, the results obtained during infection with the ΔRD1 bacteria were very variable, impeding a definite conclusion on whether the ESX-1 system was responsible for the regulation of TORC1 during M. marinum infection." (PMID 28414774, 2017). "Nevertheless, we detected a significant decrease in the recruitment of Lamtor1, Rheb and Lst8 to the M. marinum ΔRD1 MCV at 7 hpi, suggesting that the features of the bacterial compartment diverge during infection depending on the functionality of the ESX-1 system." (PMID 28414774, 2017). "Given EsxA and other ESX-1 secreted substrates are virulence factors and some of the most immunodominant proteins during infection we examined the number of recruited T cells, in vivo cytokine expression and gross pathology in animals infected with M.tb Erdman or M.tb DK9897." (PMID 28436493, 2017). "Moreover, the upregulation of autophagy genes early after infection was also strictly dependent on a functional ESX-1 secretion system." (PMID 28414774, 2017). "So far, Mtb-induced phagosomal rupture has only been observed atlater stages of infection, i. e, 3–5 dpi, akinetic situation, which cannot explain the very early, ESX-1-dependent release oftype I IFNs or IL-1β, that requires recognition of mycobacterial components bythe host cytosolic sensors." (PMID 25658322, 2015). "In conclusion, Mtb ESX1-fractalkine-mediated CD11b+ cellular migration may play a role in establishment of a foothold in initial infection, maintenance and spread of bacilli through niche expansion." (PMID 24631198, 2014). "It has been shown that infection by M. tuberculosis and M. marinum may induce ESX-1-dependent NLRP3 inflammasome activation." (PMID 22558425, 2012). "Furthermore, after the initial acute phase of infection (≥28 days), both wild type and ΔRD1 bacilli persisted equally well, with little pathology in tails of infected animals, suggesting Esx-1-independent establishment of latent disease." (PMID 20463815, 2010). "The observation that not only does H37Ra over-express only a small subset of these fifty genes (filled bars), but also represses the expression of others, highlights the importance of both ESX-1 and phoP-regulated genes during a successful infection by virulent bacilli." (PMID 20548782, 2010).